ALB (albumin)
Diseases named in the same sentence as ALB in open-access papers (continued):
Sharing a sentence is not in itself a finding about the gene and the disease.
type 2 diabetes (continued). "Participants with CKD (estimated glomerular filtration rate [eGFR] 25–75 ml/min per 1.73 m2; urinary albumin-to-creatinine ratio 200–500 mg/g), with or without type 2 diabetes, were randomized 1:1 to dapagliflozin 10 mg or placebo, once daily." (PMID 35257056, 2022). "Among age, sex, AFP, albumin, CP score, receipt of surveillance, platelets, total bilirubin, type 2 diabetes, and initial tumor size, we found that higher AFP (P = 0.048), lower albumin at presentation (P = 0.028), and lower initial tumor size (P = 0.025) were associated with higher TGR." (PMID 34966854, 2021). "Convenient nonfasting alternatives for type 2 diabetes testing are other glycated proteins (eg, glycated albumin, fructosamine, and other advanced glycation end products) either in combination with or in place of HbA1c." (PMID 33705304, 2021). "Albumin was isolated from patients with type 1 and type 2 diabetes (T1D and T2D, respectively) and from non-diabetic control subjects." (PMID 34178389, 2021). "In the type 2 diabetes study, the ANGPTL8 level was found to be related to urinary albumin excretion, and there was a positive correlation between serum ANGPTL8 and urinary albumin/creatinine levels (r = 0.427, P < 0.001)." (PMID 33853533, 2021). "Urine samples from 77 patients with either type 1 or type 2 diabetes and 97 non-diabetic controls were tested for T-AN, H-AN, albumin and creatinine." (PMID 32985540, 2020). "This was an observational cohort study of 31,931 patients with and 33,201 age/sex matched patients without type 2 diabetes (T2D) who had a serum creatinine and urine albumin-to-creatinine ratio (UACR) or dipstick proteinuria (DP) values." (PMID 32380961, 2020). "We also note that a very recent report has revealed that extensive glycation dramatically reduces the zinc-binding ability of albumin; therefore both high FFA and high blood glucose may work together to adversely affect zinc speciation in type 2 diabetes." (PMID 30266430, 2019). "Increases in serum albumin protected against the transition from prediabetes to overt type 2 diabetes in subjects without MetS." (PMID 28430803, 2017). "Further adjustment for systolic blood pressure, plasma aldosterone, plasma albumin, plasma magnesium, hs-CRP, type 2 diabetes, smoking, alcohol, education, race, urinary creatinine excretion, plasma chloride, or the BUN/creatinine ratio did not materially alter the association." (PMID 28346526, 2017). "Several studies investigated the relationship between urinary albumin excretion and ocular factors in non-glaucomatous patients with type 2 diabetes." (PMID 28006020, 2016). "Long-term low-dose aspirin does not affect eGFR and positive urine dipstick albumin in patients with type 2 diabetes." (PMID 26808136, 2016). "Moreover, in patients with type 2 diabetes, insulin infusion reduced the levels of eotaxin and MCP-1, and the eosinophil count is also related to albumin excretion in males." (PMID 24423092, 2014). "The aims of this study were to estimate the prevalence of left ventricular systolic (LVSD) and diastolic (LVDD) dysfunction, and to test if BNP and urinary albumin excretion rate (AER) are related to LVSD, LVD and left ventricular mass (LVM) in asymptomatic type 2 diabetes patients." (PMID 20078898, 2010). "The current study indicates that several serum biomarkers could be predictive for CAD in patients with type 2 diabetes, among which serum levels of hs-CRP and glycated albumin appeared to be useful in clinical practice." (PMID 17178005, 2006). "However, clinical trials showing positive kidney-protective efficacy in patients with CKD without type 2 diabetes included only patients with high urine albumin–creatinine ratio (UACR; >200 mg/g), resulting in little evidence for patients with low UACR." (PMID 39165293, 2024).
type 2 diabetes (continued). "Glomerular hyperfiltration, early kidney disease (microalbuminuria: urine albumin-excretion ratio (UAER) 30 to 300 mg/d), overt kidney disease (macroalbuminuria: UAER > 300 mg/d), and ESRD are the stages of disease that are common to both type 1 and type 2 diabetes." (PMID 36204481, 2022). "In another study, FGM was used in 18 hemodialysis patients with type 2 diabetes, but the focus was on glycated hemoglobin, as FGM readings were used to compute an estimated glycated hemoglobin value (eHbA1c) to be compared with eHbA1c derived by glycated albumin, BMI, and hemoglobin." (PMID 34395456, 2021). "CWJI has a protective effect in type 2 diabetes (T2DM) patients with persistent microalbuminuria and normal blood pressure by inhibiting kidney endothelin (ET) synthesis, reducing the level of urinary albumin excretion (UAE), plasma ET concentration, and urinary ET excretion." (PMID 34790246, 2021). "Furthermore, urine KIM-1 level has been shown to increase independent of albumin and to serve as a marker of renal tubular injury in the early period in Type 2 diabetic patients." (PMID 30035656, 2018). "Consequently, these findings above motivated us to speculate that increased circulating levels of ANGPTL8 might be positively related to urine albumin-to- creatinine ratio (ACR) and serve as a novel biomarker for diabetic kidney disease in type 2 diabetes." (PMID 30072957, 2018). "In addition, no obvious effect of albumin glycation on glibenclamide binding was seen with plasma samples from patients with type 2 diabetes." (PMID 29772022, 2018). "Oxidative stress biomarkers such as thiols, ischemia-modified albumin (IMA), glycated albumin (GA), fructosamine, and AGEs were measured in 75 patients with poorly controlled type 2 diabetes (HbA1c > 7.5%) with or without vascular disease and in 31 nondiabetic controls." (PMID 29362717, 2017). "Serum albumin levels kept increasing until the end of follow-up in prediabetic subjects who returned to normal glycemic status, whereas these measures did not change in prediabetic subjects who developed type 2 diabetes." (PMID 28430803, 2017). "Increase in serum albumin concentration might protect against early glycemic deterioration and progression to type 2 diabetes even in subjects without MetS." (PMID 28430803, 2017). "A randomized double-blind vehicle-controlled clinical pilot study recruiting 40 type 2 diabetics with microalbuminuria demonstrated that a high-dose vitamin B1 therapy (300 mg/day) for 3 months produced a regression of urinary albumin excretion without any effect on plasma glucose or HbA1c levels." (PMID 25160946, 2014). "Compared with placebo, dapagliflozin reduced urinary albumin–creatinine ratio (baseline to month 4) by 36.4% (95% confidence interval, 30.2% to 42.5%) and 20.5% (95% confidence interval, 11.6% to 29.5%) in participants with and without type 2 diabetes, respectively (P-interaction: 0.02)." (PMID 39475817, 2024). "Serum soluble Klotho (sKlotho) levels exhibit a significant negative correlation with varying degrees of urine albumin in patients with type 2 diabetes mellitus(T2DM)." (PMID 37859992, 2023). "The correlation of type 2 diabetes, obesity and age with a greater probability of suffering from ARDS as a result of SARS-CoV-2 infection that persists and progresses may in part be due to the higher affinity of the spike complex for glycated/AGE forms of serum albumin." (PMID 35456942, 2022). "Since the impact of MPV, albumin and magnesium on platelet adhesion are not earlier studied in human T2D subjects, the aim of the current study was to investigate how these factors associate with platelet adhesion in type 2 diabetes." (PMID 34078390, 2021). "Interestingly, multiple albumin protein spots in 2D-DIGE clearly indicate the undergoing differential PTM in this protein and 19 glycation sites for albumin in diabetics have been identified and related to the differential extent of hyperglycemia in type 2 diabetics." (PMID 30395577, 2018).
type 2 diabetes (continued). "It is interesting to note that insulin can influence glomerular permeability to albumin in patients with type 2 diabetes but not in healthy subjects, suggesting that disruption of the insulin signaling cascade may be sufficient for insulin to result in microalbuminuria in type 2 diabetes." (PMID 27434075, 2016). "Thus, the hypoalbuminuric effect of oral sulodexide might be particularly evident in patients with significant moderately increased urine albumin, but not evident in patients with type 2 diabetes and normoalbuminuria." (PMID 25918727, 2015). "On the other hand, glycated albumin is more sensitive to shorter term alterations in blood glucose values (due to its shorter half-life) and is not affected by changes in erythrocyte survival times nor by abnormal hemoglobin metabolism observed in some type 2 diabetes cases." (PMID 22393405, 2012). "In patients with type 2 diabetes, those with overactive bladder (OAB) and nocturnal voiding had lower serum albumin levels compared to those without." (PMID 39146317, 2024). "In this study, adult patients with or without type 2 diabetes mellitus (T2DM), eGFR 25-75 mL/min/1.73 m2, and albumin-to-creatinine ratio 200-5000 mg/g (20-500 mg/mmol) and who were on a stable tolerated dose of either ACEI or ARB were either randomized to dapagliflozin (10 mg daily) or placebo." (PMID 39816316, 2024). "There were 150 patients with DKD in the observation group (urinary albumin excretion rate (UAER) ≥ 300 mg 24 h−1), and 160 patients with a more than 10 year history of type 2 diabetes but without retinopathy and DKD (UAER < 30 mg 24 h−1) in the control group." (PMID 30110438, 2018). "The primary objective of IDEAL-2 is to examine the effect of calcitriol + ACEI or ARB therapy on urine albumin to creatinine ratio (ACR; measured in a standard clinical biochemistry laboratory) compared to ACEI or ARB therapy alone, after 26 weeks, in individuals with type 2 diabetes (T2DM)." (PMID 29665833, 2018). "The aim of this study was to investigate the relationship between urinary albumin excretion and IOP in patients with type 2 diabetes without renal impairment." (PMID 24788677, 2014). "Another trial, DAPA-CKD enrolled patients 18 years of age or older with an eGFR 25–75, a urine albumin to creatinine ration between 200 and 5,000 mg/g, and who were stable on maximum tolerated ACE inhibitor or ARB with type 2 diabetes (two thirds of patients) or without diabetes." (PMID 39950157, 2025). "Notably, in additional clinical exploration of type II diabetes, individuals with overactive bladder (OAB) manifested a substantial reduction in serum albumin levels relative to those without OAB." (PMID 39146317, 2024). "In this retrospective observational study, the urine albumin-to-creatinine ratio (ACR) and the nonalbumin protein-to-creatinine ratio (NAPCR) were measured in 325 patients with type 2 diabetes and estimated glomerular filtration rates (eGFR) ≥30 mL/min/1.73 m2." (PMID 28912839, 2017). "However, fibrinogen synthesis is also increased even in the absence of micro- or macroalbuminuria in type 2 diabetes, suggesting that plasma FIB change is not consistent with urine albumin excretion, and it is probably a more sensitive and powerful predictor for DKD." (PMID 35802685, 2022). "In linear regression models, we investigated whether TCF7L2 and CAPN10 variants were associated with phenotypic characteristics among controls without type 2 diabetes, including loge-normalized FPG, waist circumference, BMI, systolic and diastolic blood pressure and urinary albumin." (PMID 24059590, 2013).
sarcopenia (465 papers, 2014 to 2026). Progressive decline in muscle mass due to aging which results in decreased functional capacity of muscles. "Twenty‐seven studies reported the association between serum albumin and sarcopenia in patients with CKD." (PMID 41457350, 2026). "The meta‐analysis showed that per 1 g/dL increase in serum albumin was significantly associated with a reduced risk of sarcopenia overall (crude OR = 0.91; 95% CI: 0.87–0.95; I2 = 0.0%; p < 0.001; adjusted OR = 0.91; 95% CI: 0.79–1.05; I2 = 67.5%; p = 0.201)." (PMID 41457350, 2026). "Low levels of albumin have been linked to reduced muscle mass and sarcopenia, which are associated with mortality risk in centenarians." (PMID 41065185, 2025). "Regarding nutritional factors, UK Biobank data indicate that sarcopenia is closely linked to older age, inflammatory status, and reduced serum albumin levels." (PMID 40904783, 2025). "Serum albumin, a key marker of systemic protein reserve, is directly linked to sarcopenia through two pathways supported by sarcopenia-specific observations." (PMID 41280389, 2025). "Sarcopenia was associated with lower albumin levels (p = 0.038) and higher mortality rates (56.7% vs. 33.3%)." (PMID 40725756, 2025). "Univariate Cox analysis showed that sarcopenia (P = 0.029), ALB ≥ 35 g/L (P < 0.001) and SO (P = 0.007) were associated with OS." (PMID 40549046, 2025). "First, reduced albumin levels indicate insufficient dietary protein intake or impaired protein utilization—both well-documented risk factors for sarcopenia." (PMID 41280389, 2025). "The GNRI is composed of a combination of serum albumin concentration and body weight, both closely associated with sarcopenia." (PMID 41235313, 2025). "Conversely, patients with higher PVH grades exhibited lower BMI values, higher frailty screening index scores, higher frailty and sarcopenia prevalence, lower albumin levels, and nutritional risk." (PMID 41169410, 2025). "Low serum albumin is associated with increased mortality, sarcopenia, and poor functional outcomes in older adults." (PMID 41295296, 2025). "Studies suggest that low serum albumin levels are associated with muscle wasting and the presence of sarcopenia." (PMID 40686817, 2025). "Subsequently, Our correlation analysis demonstrated a significant association between sarcopenia and several biomarkers, including albumin, prealbumin, retinol-binding protein, NK cells, BMI, and PNI." (PMID 40740773, 2025). "Several studies have shown that decreased serum albumin levels are associated with reduced muscle mass and strength, increased sarcopenia risk, and poorer prognosis." (PMID 40428779, 2025). "In a study of patients with hip fracture age, polypharmacy, and low albumin levels was associated with sarcopenia." (PMID 38741067, 2024). "It should be noted that urinary albumin excretion has been associated with an increased risk of falls and has been suggested to represent a predictor of sarcopenia." (PMID 38594601, 2024). "One study that focused on patients with both sarcopenia and frailty also showed that low values of albumin and sodium were associated with higher mortality in these patients." (PMID 39795544, 2024). "Factors associated with sarcopenia in the multivariate analysis were the presence of extensive ileal disease, low serum albumin levels, and small waist circumference." (PMID 39683376, 2024). "Using Cox univariate analysis, the following variables were significantly associated with 540-day survival: age, albumin levels, presence of sarcopenia, CTP score, MELD score, AFP levels, PROSASH-II groups, and ECOG-PS." (PMID 38539416, 2024). "In a meta-analysis, low ALB levels were found to be associated with sarcopenia among older individuals." (PMID 39839409, 2024). "Lower serum albumin levels have been reported in numerous studies among individuals exhibiting clinical signs of sarcopenia and have been linked to frailty." (PMID 39692768, 2024).
sarcopenia (continued). "Age, ECOG performance status, dementia, SPPB score, and albumin level were associated with sarcopenia." (PMID 39104037, 2024). "Sarcopenia and low serum albumin level synergistically increasethe risk of incident disability in older adults." (PMID 38885304, 2024). "The development of sarcopenia in patients on PD is closely associated with reduced protein synthesis and accelerated protein degradation, which is estimated using serum albumin, pre-albumin, ferroprotein, and hemoglobin levels." (PMID 39734670, 2024). "Some studies also showed the associated factors for sarcopenia in CD patients, such as nutrition-related indicators (Low albumin level) and higher levels of inflammatory markers (CRP, ESR, and FC)." (PMID 38438954, 2024). "Using LASSO regression, we developed a nutritional AHLC (albumin + HDL cholesterol + lymphocytes + calcium) model for sarcopenia risk prediction." (PMID 39726874, 2024). "In this study, the globulin level, calf circumference, and mid-arm circumference were excluded from the regression model to mitigate collinearity with the albumin level, nutritional status, and risk of sarcopenia, respectively." (PMID 38786415, 2024). "EPSs, BMI, grip strength, total protein, and albumin were identified as useful indicators for detecting the risk of dynapenia/sarcopenia in routine psychiatric care." (PMID 39791654, 2024). "The risk of sarcopenia increases with older age, male gender, decreased Mini-Nutritional Assessment score, lower serum albumin level, and higher fat mass." (PMID 39839289, 2024). "Blood tests revealed that dynapenia and sarcopenia were associated with low total protein, albumin, and fasting blood glucose levels, indicating poor nutrition." (PMID 39791654, 2024). "So our suggestion is to screen at admission albumin, total proteins, and ions such as calcium, iron, folic acid, and vitamins for all patients above 65 years old or with risk factors for sarcopenia." (PMID 38130551, 2023). "Sarcopenia risk was independently associated with advanced age, and the risk was reduced with higher serum albumin concentrations." (PMID 37363476, 2023). "Sarcopenia risk was independently associated with patient age, and the risk of sarcopenia was low among patients with higher albumin concentrations." (PMID 37363476, 2023). "Renal parameters such as eGFR and albuminuria (spot urine albumin to creatinine ratio) were significantly associated with sarcopenia." (PMID 37685565, 2023). "Sarcopenia and Osteosarcopenia were also negatively associated with albumin (g) (p < 0.01; p < 0.05, respectively)." (PMID 37960189, 2023). "In contrast, BMI (OR 0.663; 95% CI 0.551–0.799), MAMC (OR 0.833; 95% CI 0.716–0.969), albumin (OR 0.831; 95% CI 0.762–0.907), and total cholesterol (OR 0.389; 95% CI 0.230–0.659) were negatively correlated with sarcopenia risk." (PMID 38071233, 2023). "Married patients (aOR=0.12; 95% CI: 0.03–0.49; P=0.003) and those with higher albumin concentrations (aOR=0.89; 95% CI: 0.80–0.99; P=0.046) were less likely to have increased risk of sarcopenia." (PMID 37363476, 2023). "Our study proved that CT-determined sarcopenia and low serum albumin level were independently associated with an increased rate of leukopenia and neutropenia after HIPEC." (PMID 36814253, 2023). "Sarcopenia, sarcopenic obesity and osteosarcopenia were negatively associated with albumin (%) (p < 0.001 for sarcopenia and osteosarcopenia, and p < 0.01 for sarcopenic obesity)." (PMID 37960189, 2023). "Previous studies, including our present study, found sarcopenia is associated with signs of nutritional deficiencies such as decreased hemoglobin levels, serum total protein and albumin." (PMID 37184771, 2023). "Patients were stratified into groups based on their sarcopenia and albumin status to investigate significant associations between covariates using ANOVA." (PMID 37371699, 2023).